INS (insulin)
Diseases named in the same sentence as INS in open-access papers (continued):
Sharing a sentence is not in itself a finding about the gene and the disease.
diabetes (continued). "Currently, the available apps for diabetes management can be broadly classified into 5 categories: nutrition, physical activity, blood glucose monitoring, insulin titration, and insulin injection." (PMID 39805107, 2025). "SPI1 and MTF1 were two novel upstream transcription factors identified which have been suggested to be involved in the inflammatory cascade and insulin regulation in diabetes." (PMID 39974596, 2025). "Type 2 diabetes mellitus (T2DM) is a chronic metabolic disorder characterized by insulin resistance, low-grade chronic inflammation, and insufficient insulin secretion, influenced by genetic predisposition and detrimental lifestyle choices." (PMID 41137228, 2025). "In diabetes management, prospective studies suggest that the therapeutic efficacy of these agents correlates with the capacity for endogenous insulin secretion." (PMID 41301738, 2025). "Of all participants, 113 (18.8%) took both an oral antidiabetic drug and insulin for their diabetes management." (PMID 40416402, 2025). "Diabetic cardiomyopathy (DCM), a complication of type 2 diabetes mellitus (T2DM), is closely associated with key genes in the insulin signaling pathway." (PMID 40747301, 2025). "Fiber also plays a significant role in improving insulin sensitivity, which is essential for managing diabetes and preventing its progression." (PMID 40026940, 2025). "Diabetes can influence cancer progression through mechanisms such as hyperinsulinemia, hyperglycemia, and inflammation, with elevated insulin and insulin-like growth factors (IGFs) promoting cell proliferation and tumorigenesis." (PMID 41303679, 2025). "Insulin secretory oscillations increase the efficiency of hepatic insulin signaling and are disrupted in individuals with obesity and diabetes." (PMID 39936635, 2025). "Understanding of insulin as a treatment for diabetes was high (93.01%), yet a significant portion of participants (63.64%) was unfamiliar with the role of oral hypoglycemic medications in diabetes management." (PMID 41473853, 2025). "Clinical studies suggest that vitamin D supplementation improves insulin sensitivity and reduces fasting glucose levels in individuals with type 2 diabetes mellitus (T2DM)." (PMID 40218965, 2025). "Diabetes is the most common serious metabolic disease in humans and is characterized by abnormal blood glucose due to defective insulin secretion or insulin resistance." (PMID 41013190, 2025). "This study aims to compare the efficacy and safety profile of insulin initiation with Gla-300 when administered during the day versus at night in adult type 2 diabetes mellitus (T2DM) patients." (PMID 40190894, 2025). "In summary, this study highlights that post-coital hypoglycemia is a prevalent and under-recognized complication in diabetes, driven primarily by insulin use and T1DM status, but also influenced by demographic and behavioral factors." (PMID 41030722, 2025). "To date, the patient has an excellent performance status (ECOG 0), transaminase levels maintained within normal ranges, and diabetes is well controlled with basal–bolus insulin therapy." (PMID 40729244, 2025). "Since differentially expressed genes are also involved in insulin secretion and diabetes-related pathways, it suggests to some extent the organ-specific coupling of neuroendocrine-nociceptive transmission." (PMID 41132793, 2025). "Psychological insulin resistance (PIR) is a broad concept that covers multiple factors involved in the refusal of insulin as a treatment option for management of diabetes." (PMID 40336418, 2025). "These compounds help to regulate alpha-amylase, alpha-glucosidase, and insulin levels, making the plant effective for treating diabetes." (PMID 40365188, 2025). "Type 1 diabetes mellitus (T1DM) is predominantly caused by autoimmune processes and requires lifelong insulin therapy." (PMID 41373820, 2025).
diabetes (continued). "A significant breakthrough in diabetes research was the discovery of the role of insulin in glucose metabolism in the early 1920s." (PMID 41280745, 2025). "CS17919 also slightly increased insulin sensitivity compared with the model group, indicating its therapeutic potential in diabetes." (PMID 38873818, 2025). "IGI measures the extent to which insulin is produced in response to glucose load, and low IGI indicates impaired first phase of insulin secretion which is a predictor of diabetes." (PMID 40367203, 2025). "The 6 major aspects of diabetes self-management are physical activity, nutrition, blood glucose testing, medications or insulin injections, health feedback, and education." (PMID 39805107, 2025). "This randomized, open-label, parallel-controlled trial investigated the efficacy and safety of needle-free injection (NFI) compared to conventional insulin pen (CIP) in patients with type 2 diabetes mellitus (T2DM) undergoing intensive insulin therapy." (PMID 41585790, 2025). "Dysregulation of insulin production or impaired insulin function can lead to metabolic disorders, notably diabetes." (PMID 40796375, 2025). "People with Type 1 diabetes need constant tracking and exact insulin administration for their diabetes management." (PMID 41280718, 2025). "We also tested diabetes associated indicators and observed decreased glucagon and PAI-1 and increased insulin levels, suggesting nicotine restored glucose disposal ability." (PMID 41488304, 2025). "Children demonstrated notable gains in diabetes basics, dietary management, decision-making, insulin administration, blood glucose monitoring, physical activity, and psychosocial well-being." (PMID 41339733, 2025). "Given the increasing prevalence of diabetes and the aging population, understanding the challenges and outcomes of insulin pump therapy in the elderly is critical." (PMID 41473654, 2025). "Diabetes is a metabolic disorder characterized primarily by hyperglycemia, resulting from insulin resistance or inadequate insulin secretion." (PMID 40647186, 2025). "Forty percent of the patients had more than 10 years since their diabetes diagnosis, and 31.9% used insulin alone or in combination with oral antidiabetic drugs as treatment." (PMID 40966218, 2025). "This strategy, often referred to as “bugs asdrugs”, includes innovative applications like engineering bacteriato produce insulin directly in the gut to treat diabetes." (PMID 40888536, 2025). "This chapter explores the role of ASs in diabetes management, with a special focus on their mechanisms of action, including modulation of insulin sensitivity and glucose metabolism." (PMID 40873447, 2025). "Diabetes management will likely involve advancements in smart insulin, personalized medicine, beta cell regeneration, and increased use of digital health through artificial intelligence." (PMID 40507585, 2025). "These examples underscore how the integration of molecular diagnostics into clinical practice can optimize management, prevent unnecessary insulin use, and improve long-term outcomes in pediatric patients with monogenic diabetes." (PMID 41367630, 2025). "Type 2 diabetes mellitus, characterized by insulin insensitivity and a comparative insulin shortage, is the most common chronic metabolic disorder affecting global health." (PMID 40565712, 2025). "Effective diabetes care necessitates a multifaceted approach involving insulin therapy, non-insulin anti-diabetic drugs and lifestyle adjustments." (PMID 40489012, 2025). "When insulin secretion is compromised, it can lead to diabetes mellitus, characterized by hyperglycemia, dyslipidemia, and subsequent long-term damage to tissues." (PMID 40906536, 2025). "MO benefits CDs like diabetes, cardiovascular diseases, arthritis, and cancer by improving insulin sensitivity, reducing blood glucose levels, and protecting against hyperglycemia-induced organ damage." (PMID 40149610, 2025).
diabetes (continued). "These compounds are believed to enhance insulin sensitivity and offer protection against oxidative stress, a key contributor to diabetes-related complications." (PMID 41011114, 2025). "Diabetes is a complex metabolic disorder characterized by hyperglycemia, insulin resistance, and insufficient insulin secretion." (PMID 40599237, 2025). "In patients with diabetes (comorbid with a heart failure condition), exercise like a structured walking program helps in the clearance of glucose from the body in both insulin-dependent (T1D) as well as insulin-independent (T2D) conditions." (PMID 40868903, 2025). "T2DM constitutes more than 95% of diabetes cases and is a result of insulin resistance coupled with β-cell insulin secretion dysfunction." (PMID 40125513, 2025). "Regarding diabetes treatment, 71.9% (115/160) of the patients were treated with OADs alone, whereas 28.1% (45/160) of the patients were on insulin regimens, either alone or in combination with OADs." (PMID 40896837, 2025). "The main pathological condition of diabetes mellitus is insulin resistance due to the accumulation of visceral fat and decreased skeletal muscle mass, with preservation of endogenous insulin secretion." (PMID 40951209, 2025). "Over the past decade, the advent of continuous and intermittently scanned continuous glucose monitoring (CGM and isCGM) devices has been associated with reduction in glycated haemoglobin (HbA1c) levels in both children and adults with insulin‐treated diabetes." (PMID 39718005, 2025). "One of the most exciting potential applications for chitosan lies in the delivery of insulin for patients with diabetes." (PMID 40352348, 2025). "Type 1 diabetes mellitus (T1DM) results in the pancreas being unable to produce insulin, which is a hormone that helps regulate blood glucose levels." (PMID 41373306, 2025). "Diabetes was managed with injectable insulin in 94 patients (53.4%) and oral medications in 82 (46.6%)." (PMID 41383356, 2025). "In this study, we aimed to analyze the feasibility of utilizing SWE and SWD to evaluate the individual need for initiating insulin therapy in patients with type 2 diabetes mellitus (T2DM)." (PMID 40710394, 2025). "It is characterised by elevated blood glucose levels due to insufficient insulin production or ineffective insulin use, and includes Type 1, Type 2, gestational, and rarer forms like monogenic diabetes and latent autoimmune diabetes in adults (LADA)." (PMID 40559479, 2025). "Among patients with diabetes, those on insulin therapy had significantly higher levels of glucated hemoglobin A1c than patients on oral antidiabetic drugs." (PMID 41464751, 2025). "The use of CGM in people with insulin-treated diabetes has been shown to improve HbA1c, increase time spent in the target glucose range of 3.9 to 10 mmol/L, reduce risk of hypoglycaemia, and improve patient-reported outcome measures." (PMID 41395259, 2025). "Harmine also rapidly enhances glucose-stimulated insulin secretionin vitroandin vivo, reversing diabetes within days in diabetic mice transplanted with a marginal mass of human islets." (PMID 41573826, 2025). "Inhibition of pancreatic KATP channels is the pharmacological mechanism by which oral sulfonylurea drugs increase insulin release in patients with diabetes." (PMID 40650956, 2025). "DmCpGs and DMRs were identified in genes related to insulin-regulation, glucose metabolism, obesity traits, adipogenesis, fat-metabolism, diabetes, asthma, lung function, telomere maintenance, body form and aging." (PMID 40410506, 2025). "Insulin resistance serves as an early characteristic of diabetes, primarily characterized by a diminished ability to process glucose and reduced insulin sensitivity." (PMID 39761309, 2025). "Treatment of rodent diabetes models with IL-1 signaling inhibitors or antibodies targeting IL-1β has also been shown to improve insulin sensitivity." (PMID 39940855, 2025).
diabetes (continued). "In the Ins2Akita mouse model of insulin-dependent diabetes, tryptophan and indole-3-carbinol alleviate diabetes-induced intestinal barrier dysfunction, insulin resistance, systemic inflammation and FMO3/ICAM expression." (PMID 41440753, 2025). "This article includes a thorough review of insulin icodec’s safety and efficacy in type 1 and type 2 diabetes mellitus including its pharmacokinetic and pharmacodynamic profile." (PMID 40156735, 2025). "Brittle diabetes, characterized by severe glycemic variability and insulin sensitivity, is rare in T3cDM." (PMID 41146800, 2025). "Notable links to inadequate glycemic control were found in connection with older age, a longer duration of diabetes mellitus, insulin therapy and diagnosis of hypertension." (PMID 40078898, 2025). "In the realm of pediatric diabetes, AI algorithms have been explored for predicting hypoglycemic events, optimizing insulin dosing, personalizing dietary recommendations, and identifying risk factors for disease progression." (PMID 40895926, 2025). "In contrast to patients with diabetes treated with insulin or secretagogues, hypoglycemia is a rare condition in people without diabetes." (PMID 40161293, 2025). "The results of the included studies are aligned with previous evidence from outpatient settings, where CGM is widely accepted as the standard of care for insulin-treated diabetes, and increasingly recommended in perioperative and long-term care environments." (PMID 41517284, 2025). "She had previously been diagnosed with hypertension, hyperlipidemia, and type 2 diabetes mellitus, for which she was already being treated with a beta blocker and insulin prior to admission." (PMID 41589173, 2025). "Diabetes mellitus (DM) is a chronic metabolic condition characterized by elevated blood sugar levels resulting from inadequate insulin synthesis, insulin resistance, or both." (PMID 40074983, 2025). "Diabetes management is still complicated by the necessity of individualized lifestyle modification, self-monitoring, and insulin management, all factors that are strongly influenced by socioeconomic and behavioral determinants." (PMID 41446498, 2025). "In the basic theme quadrant, the red circle covers metabolic foundations such as obesity, adipose tissue, diabetes, liver, type 2 diabetes, high-fat diet, liver fibrosis, insulin sensitivity, metabolism, and FGF21." (PMID 40868109, 2025). "Diabetes is a chronic disease characterized by hyperglycemia resulting from an impairment in insulin secretion and/or function." (PMID 40125513, 2025). "This provides valuable insights into the complex interplay between prostaglandins, potassium channels, and insulin secretion, contributing to our understanding of pancreatic islet function and potential implications for diabetes mellitus." (PMID 40028769, 2025). "Akkermansia muciniphila enhance insulin sensitivity and glucose tolerance through anti-inflammatory mechanism, offering protective effects against type 2 diabetes mellitus (T2DM)." (PMID 40906081, 2025). "Diabetes mellitus is a chronic metabolic condition marked by consistently high blood glucose levels, which typically result from either insulin resistance or inadequate insulin secretion." (PMID 40005141, 2025). "These metabolic improvements are accompanied by enhanced insulin sensitivity, supporting their potential for the simultaneous treatment of glycemic and lipid abnormalities in patients with type 2 diabetes mellitus (T2DM)." (PMID 41012462, 2025). "Studies in rats have shown that this technique not only normalizes blood glucose and insulin levels in response to various stimuli but also reverses serious diabetes-related complications, including diabetic nephropathy and retinopathy." (PMID 40428118, 2025). "Damage to or a reduction in the function of these cells can lead to insufficient insulin secretion, resulting in diabetes." (PMID 40453655, 2025).
diabetes (continued). "Estimated changes in insulin dosing with GLP-1 receptor agonist therapy, showing overall among all countries regardless of sample size, and the subset of countries with N > 100 people with diabetes reporting insulin use." (PMID 40245017, 2025). "Diabetes cohorts for serum insulin (5 studies; 154 vs. 151) revealed a pooled SMD of −0.33 (95% CI −0.77 to 0.11), which was non-significant with high heterogeneity (I2 ≈ 75%, p < 0.01)." (PMID 41517125, 2025). "Blood glucose self-monitoring is crucial for individuals with diabetes mellitus and on insulin therapy to ensure safe glycemic control and optimal treatment outcomes." (PMID 41476921, 2025). "Diabetes is a metabolic disorder characterized by insufficient insulin production, leading to elevated blood glucose levels." (PMID 40906303, 2025). "Its objective is to provide an alternative to manual insulin injections for individuals with diabetes by simulating and augmenting the pancreas’ natural hormone production." (PMID 39869550, 2025). "Given the widespread clinical use of insulin products among individuals with diabetes, a multivariate MR analysis was conducted to identify potential bias from treatment factors, specifically the use of insulin products, in the reverse analysis." (PMID 40299325, 2025). "Diabetes mellitus (DM) is a metabolic disorder characterized by chronic hyperglycemia resulting from impaired insulin secretion or action." (PMID 40832613, 2025). "We focused on vertebrate-like conoinsulins G3c, G4b, and G7 due to their overall structural similarity to human insulin and insulin’s clinical significance in treating diabetes." (PMID 40796375, 2025). "Almost half of the patients with diabetes were treated with metformin alone (47%), 42% with metformin and insulin, 5% with sulfonylurea only, 3% with an SGLT-2 inhibitor only, and 3% with diet only." (PMID 40868983, 2025). "This versatility makes gelatin an ideal candidate for both oral and injectable insulin therapies, which are essential for managing diabetes effectively." (PMID 40352348, 2025). "In diabetes, beta cells are in a vicious cycle wherein an impaired insulin response to glucose produces hyperglycaemia, which stresses cell function and limits efficiency." (PMID 40133488, 2025). "Its numerous action mechanisms of augmenting insulin secretion, plummeting oxidative stress, improving insulin sensitivity, and refining glucose uptake make M. oleifera a fantastic natural drug for treating diabetes." (PMID 40248126, 2025). "All 11 EP members agreed that a structured educational pathway is needed to train diabetes educators in the use of the MiniMedTM 780G insulin pump system, including PWT1D on the system and providing ongoing support for these users." (PMID 39470803, 2025). "The therapeutic algorithm for diabetes mellitus prioritizes metformin as the foundational pharmacotherapy, with subsequent pharmacotherapeutic options stratified into insulin preparations and oral antihyperglycemic agents." (PMID 40648562, 2025). "Diabetes mellitus (DM) encompasses a spectrum of metabolic disorders characterized by chronic hyperglycaemia resulting from defects in insulin secretion, action, or both." (PMID 40970045, 2025). "Diabetes mellitus (DM) is a prevalent chronic metabolic disorder characterized by hyperglycemia resulting from impaired insulin secretion, insulin action, or both." (PMID 41356947, 2025). "Regarding management, 37.8% of participants were treated with oral hypoglycemic agents, 24.2% with insulin injections, 22% with a combination of oral agents and insulin, and 16% managed their diabetes through dietary modification alone." (PMID 41464418, 2025). "Participants using insulin or other diabetes medications had the highest mean ranks on SBQ (118.30), Apfel (120.80), and VAS (121.70), followed by participants taking blood pressure medications." (PMID 41583312, 2025).